INO80D (INO80 complex subunit D)
Description:
Putative regulatory component of the chromatin remodeling INO80 complex which is involved in transcriptional regulation, DNA replication and probably DNA repair.
Synonyms: FLJ20309
Tractability: PROTAC: UniProt records ubiquitination sites on it.
Gene: Protein-coding gene on chromosome 2 (205,993,721 to 206,086,303, reverse strand). Ensembl gene ENSG00000114933.
Subcellular location: Nucleus
Pathways (Reactome):
DNA Repair: DNA Damage Recognition in GG-NER
Metabolism of proteins: UCH proteinases
Gene Ontology:
Biological process: chromatin remodeling; positive regulation of DNA-templated transcription; regulation of cell cycle; regulation of chromosome organization; regulation of DNA replication; regulation of DNA strand elongation; positive regulation of DNA repair; positive regulation of telomere maintenance in response to DNA damage; regulation of DNA repair; regulation of embryonic development; telomere maintenance
Cellular component: Ino80 complex; nucleoplasm; nucleus
Genetic constraint (gnomAD): Loss-of-function variants: 20 observed, 82.76 expected, observed/expected ratio (o/e) 0.24, 90% interval 0.17 to 0.35. The upper end of that interval is the gene's LOEUF score, 0.35, which puts it in group 1 of 6, group 1 being the genes least tolerant of losing a copy. Missense variants: 977 observed, 1,323.9 expected, observed/expected ratio (o/e) 0.74, 90% interval 0.7 to 0.78. Synonymous variants: 438 observed, 509.83 expected, observed/expected ratio (o/e) 0.86, 90% interval 0.79 to 0.93.
Homologues: Orthologues: chimpanzee INO80D (99% identical), macaque INO80D (99% identical), pig INO80D (98% identical), dog INO80D (97% identical), rabbit INO80D (96% identical), rat Ino80d (95% identical), mouse Ino80d (94% identical), tropical clawed frog ino80d (76% identical), zebrafish ino80da (53% identical), Drosophila melanogaster l(3)L1231 (18% identical), Caenorhabditis elegans sumv-1 (13% identical).
Diseases named in the same sentence as INO80D in open-access papers:
INO80D is named in the same sentence as 5 diseases in open-access papers, as found by Europe PMC text mining. Sharing a sentence is not in itself a finding about the gene and the disease. The quoted sentences say what the papers report.
colorectal cancer (1 paper, 2016). A primary or metastatic malignant neoplasm that affects the colon or rectum. "Other candidates, PARG and TDGF1, have been associated with cancer regulation; however, the functional role of the candidates HORMAD1, PIGC, NCAM2, INO80D, SLCO2A1, SLC12A1, and METTL19 was unclear in colorectal cancer." (PMID 27383761, 2016).
glioma (1 paper, 2025). A benign or malignant brain and spinal cord tumor that arises from glial cells (astrocytes, oligodendrocytes, ependymal cells). "In our selection of seven HRD-related genes, the high expression of PLK3, PRMT6, UNG, and FANCB is associated with poorer prognosis in glioma patients, whereas the high expression of POLR2F, INO80D, and PTEN is linked to better prognosis." (PMID 41417782, 2025). "For instance, genes like UNG and PLK3 play a significant role in most glioma cell lines, whereas PTEN and INO80D exhibit a weaker influence in the majority of cell lines." (PMID 41417782, 2025).
osteoporosis (1 paper, 2022). A condition of reduced bone mass, with decreased cortical thickness and a decrease in the number and size of the trabeculae of cancellous bone (but normal chemical composition), resulting in increased fracture incidence. "Target genes with the highest number of miRNAs were DGKH, TNRC6B, ZNF704, INO80D and NFAT5, but according to the literature, none of these were ever directly associated with PTH or osteoporosis." (PMID 36011354, 2022).
tumor (1 paper, 2025). "INO80D is an essential regulator for chromatin remodeling and genome integrity and we reasoned that it acts as a tumor suppressor." (PMID 41123786, 2025).
INO80D also shares sentences with these, for which no sentence is quoted: cancer (1 paper).